CACYBPP2 (calcyclin binding protein pseudogene 2)
Gene: Processed pseudogene on chromosome 2 (183,607,442 to 183,608,119, reverse strand). Ensembl gene ENSG00000177855.
Diseases named in the same sentence as CACYBPP2 in open-access papers:
CACYBPP2 is named in the same sentence as 1 disease in open-access papers, as found by Europe PMC text mining. Sharing a sentence is not in itself a finding about the gene and the disease. The quoted sentences say what the papers report.
schizophrenia (1 paper, 2018). A major psychotic disorder characterized by abnormalities in the perception or expression of reality. "This SNP maps near the pseudogene CACYBPP2, between the nucleoporin NUP35 and the zinc finger protein ZNF804A, a candidate for ASD, schizophrenia, and other neuropsychiatric disorders." (PMID 30134952, 2018).